KLF5 (KLF transcription factor 5)
Diseases named in the same sentence as KLF5 in open-access papers (continued):
Sharing a sentence is not in itself a finding about the gene and the disease.
cancer (continued). "We also identified motifs for several transcription factors (TFs) in MYB-binding DNA sequences, including AP1, KLF5, ETS1, FOXA1 and other cancer-related TFs, suggesting that these TFs may work together with MYB in transcriptional regulation." (PMID 40234694, 2025). "KLF5 was found to exhibit widespread SNV and CNV events across multiple cancer types." (PMID 41583492, 2025). "The KLF family of transcription factors, including both KLF4 and KLF6, have a well‐established role in cancer progression, and we showed direct regulation of CFTR by KLF5 in airway epithelial cells where this factor has a critical role in wound repair and innate immunity." (PMID 40785146, 2025). "In Smad4-positive cancer cells, KLF5 is downregulated and Sox4, in the absence of KLF5, induces apoptosis by upregulating pro-apoptotic factors." (PMID 38569937, 2024). "Using public databases in GEO and TCGA, we found that the mRNA expression level of KLF5 positively correlated with that of FGF-BP1, which could bind to fibroblast growth factors such as FGF2, thus promoting the progression of cancer disease, including ESCC." (PMID 38087142, 2023). "KLF5 has also been reported to be lost in ESCC in a recent study, and overexpression of KLF5 in esophageal epithelia in vivo leads to promoting cell proliferation without squamous dysplasia or carcinoma." (PMID 38087142, 2023). "There is a negative relationship between autophagy and KLF5 in cancer, so that KLF5 provides poor prognosis and autophagy inhibition." (PMID 35317831, 2022). "Regarding the predicted pharmacodynamic profile of compounds, we concluded that all complexes presented affinities for Transcription intermediary factor 1-alpha, and Kruppel-like factor 5 (KLF5 transcription factor), both critically involved in cancer evolution." (PMID 36015318, 2022). "Finally, we selected a conservative TF kruppel-like factor 5 (KLF5) and malignant tumor-specific TF POU class 2 homeobox 2 (POU2F2) and analyzed their expression in each type of malignant tumor samples." (PMID 34722892, 2021). "Conservative TF KLF5 and specific TF POU2F2 were chosen to exhibit the expression of all malignant tumors through a beeswarm package, which also could distinguish malignant tumor-specific TFs from conservative TFs." (PMID 34722892, 2021). "Moreover, SREBF1 shows a noncanonical, SCC-specific function by cooperating with TP63/KLF5 to regulate hundreds of cis-regulatory elements across the SCC epigenome, which converge on activating cancer-promoting pathways." (PMID 34272396, 2021). "KLF5, an oncogene and a transcriptional activator located in chromosome 13q22.1, has been reported as an HPV integration hotspot gene in other HPV-related cancers." (PMID 34885212, 2021). "Among the most representative candidate cancer driver genes are HNRNPL, KLF5, and TFDP1." (PMID 31925297, 2020). "Since c-Myc, KLF5, and DRD2 have been suggested to increase cancer stem cell-like populations in various tumors, reducing these proteins in response to BPD and TFP suggests a novel FOXO3-dependent mechanism underlying BPD- and TFP-induced apoptosis in TNBC cells." (PMID 27283899, 2016). "Although previous reports have shown the involvement of Klf5 in controlling cell proliferation in several cancer cell lines, Klf5 knockdown did not affect C2C12 cell proliferation." (PMID 27743478, 2016). "KLF5 (Krüppel-like factor 5), a member of the Krüppel-like factor (KLF) family, has been shown to play important roles in the development of several types of human cancers by modulating the transcription of its target genes." (PMID 25170806, 2014). "In addition, other (cancer) ‘stemness’ genes (like LGR4, SOX9, KLF5 and MET) are also upregulated in the pSP." (PMID 24069258, 2013). "Yet, no dysplasia, polyps, or cancers developed in Villin-Klf5 mice up to at least 12 months of age, suggesting that KLF5 alone is not sufficient to induce cancer in the intestine." (PMID 22675454, 2012).
cancer (continued). "Indeed, KLF5 inhibition decreases the expression of several HIF-1-regulated genes in cancer cells, while HIF-1 inhibition affects KLF5 expression." (PMID 21951574, 2011). "We found that KLF5 did not affect E2F1 expression, and therefore, we suggest that KLF5 may play a part in promoting cancer by inactivating RB1 by regulating the expression of Cyclin D 1 and XPO1." (PMID 39888288, 2025). "Furthermore, KLF5 is a potent therapeutic target for BLBC and other cancers." (PMID 36923542, 2023). "Moreover, we find that SREBF1 cooperates with TP63/KLF5 to regulate hundreds of cis-regulatory elements across the SCC-specific epigenome, which converges on activating cancer-promoting pathways, uncovering SREBF1 as a potential therapeutic target and prognostic marker in SCC." (PMID 34272396, 2021). "KLF5-null cancer cells, which do not have Ac-KLF5, also have less TRAP + osteoclasts." (PMID 33731701, 2021). "In addition, we noticed seven of them have been included in the latest version of The Network of Cancer Genes35 (KLF5, OXA1L, RBM39, and TFDP1) or CancerMine36 (HNRNPL, KLF5, PAFAH1B1, SYT13, TFDP1), two manually curated cancer gene databases, further confirming our findings." (PMID 31925297, 2020). "In addition, we detected some other ‘cancer stemness’ markers (e.g. LGR4, SOX9, KLF5, MET) as well as pancreatic embryogenesis-related factors which may be re-initiated in CSC (e.g. HNF4A)." (PMID 24069258, 2013). "Furthermore, based on our analysis of DepMap data, targeting KLF4 in ARID1A-deficient cancer cells does not appear to influence the fitness of ARID1A mutant cell lines, further highlighting the specificity of the effect of loss of KLF5 on ARID1A -deficient cells." (PMID 39779698, 2025). "Patients with CNV in KLF5, ZFHX3 and CDH1 had reduced cancer-specific survival, compared to patients without CNV in these genes (pairwise p = 0.028, 0.026, 0.044, respectively)." (PMID 28915599, 2017). "However, patients with CNV in specific genes, such as ZFHX3, KLF5 and CDH1, had reduced cancer-specific survival compared to patients without CNV in these genes." (PMID 28915599, 2017). "However, patients with copy number gains in KLF5, ZFHX3 and CDH1 had reduced cancer-specific survival, compared to patients without CNV in these genes ZFHX3 and CDH1, respectively (pairwise p ≤ 0.044)." (PMID 28915599, 2017). "As KLF5 also directly activates transcription of CDH1, downregulation may indirectly play in favor of a progressive phenotype of certain cancer types, but not all." (PMID 24429391, 2014).
cardiovascular diseases (14 papers, 2011 to 2026). "Studies have reported that KLF4 and KLF5 are correlated with several cardiovascular diseases, but population-based studies on associations between HT and KLF4 or KLF5 have rarely been reported." (PMID 39187911, 2024). "This study highlights the potential of KLF5 inhibition as a therapeutic strategy in cardiovascular disease." (PMID 41526530, 2026). "The crucial role of KLF5 in cardiovascular diseases has been first reported in 2002; since then, newly updated data have dug out more details of its role in diverse cellular processes and provided novel thinking for treatment application." (PMID 33493334, 2021). "Krüppel-like factor 5 (KLF5) has been identified as a significant factor in cardiovascular diseases during the last two decades." (PMID 33493334, 2021). "miRNAs regulate both the expression and activities of KLF5, and miRNA therapies have shown successful outcomes of cardiovascular disorders in preclinical experiments." (PMID 33493334, 2021). "Co-immunoprecipitation, mass spectrometry, and RNA sequencing can be used to identify nuclear proteins and RNA directly interacted with KLF5 in cardiovascular diseases." (PMID 33493334, 2021). "KLF5 is a zinc-finger transcription factor which plays a role in the vascular remodelling seen in cardiovascular diseases." (PMID 28100233, 2017). "In a similar way to cardiovascular disease KLF5 expression was increased in COPD pulmonary vessels suggesting a possible role in the small vessel disease seen in these patients." (PMID 28100233, 2017). "The expression of KLF5 is activated in cardiac fibroblasts and contributes to tissue remodeling in cardiovascular diseases." (PMID 26792671, 2016). "Krüppel-like factor 5 (KLF5) is a zinc-finger transcription factor that contributes to tissue remodeling in cardiovascular diseases." (PMID 26792671, 2016). "KLF5 has been identified as a crucial factor in cardiovascular diseases." (PMID 38474039, 2024). "KLF5 is a vital mediator in the occurrence of cardiovascular diseases." (PMID 34925646, 2021). "Drugs like acyclic retinoid, which was demonstrated to alleviate the activity of KLF5, may become a potential therapy for cardiovascular diseases." (PMID 33493334, 2021). "KLF5 has been found consistently up-regulated in cardiovascular diseases." (PMID 23785430, 2013). "KLF5 could also be developed as a biomarker for diagnosis in cardiovascular diseases." (PMID 33493334, 2021).
infection (13 papers, 2013 to 2025). The state of being infected such as from the introduction of a foreign agent such as serum, vaccine, antigenic substance or organism. "Consistently, Klf5 mRNA levels were transiently elevated in the livers of WT mice following L.m. infection, suggesting that Klf5 expression plays a role in the early transcriptional response to infection." (PMID 41377671, 2025). "In this study, we first found that infection with PEDV enhanced the FSTL1 expression through the transcription factor KLF5." (PMID 39670742, 2025). "Considering that both PC-3 and DU 145 cell lines express a relatively lower level of KLF5, we also overexpressed KLF5 by lentiviral infection in these two cell lines and performed HuVEC tube formation assay with conditioned media." (PMID 25896712, 2015). "The current data demonstrate that KLF5 is upregulated in gastric epithelial cells in vitro and in vivo following infection with H. pylori." (PMID 23372710, 2013). "This population of KLF5+, Lrig1+ cells increased significantly in H. pylori-infected compared to uninfected tissues at both 4 weeks and 8 weeks post-infection." (PMID 23372710, 2013). "Concordant with increased levels of KLF5 transcript, H. pylori significantly upregulated KLF5 protein expression, which peaked between two and eight hours post-infection." (PMID 23372710, 2013). "To determine whether Klf5 is necessary for Tgr5 induction during infection, we performed siRNA-mediated knockdown of Klf5 in BMDMs." (PMID 41377671, 2025). "H. pylori significantly increased KLF5 mRNA expression two hours post-infection." (PMID 23372710, 2013). "Expression of KLF5 in gastric epithelial cells from uninfected and infected mice was evaluated by flow cytometry, which demonstrated a significant increase in the percentage of KLF5+ cells in H. pylori-infected mice at 72 hours and 1 week post-infection, prior to the development of inflammation." (PMID 23372710, 2013). "However, SRPK1 expression might be increased after 10 d of symptom onset, and the expression of KLF5 significantly differed between severe patients in the early and late stages of infection." (PMID 38262689, 2024). "Other upstream regulators such as CLU, KLF5, SP1 and TCF7L2 that were inhibited by ΔhtrA mutant infection have also been previously shown to be involved in apoptosis regulation." (PMID 37193047, 2022). "During infection with the ΔhtrA mutant, CBX5 was activated and CLU, KLF5, SP1, TCF7L2 and UBE2I were inhibited." (PMID 37193047, 2022). "Here, we identified that NOD1 silencing reversed the upregulation of KLF5 expression caused by P. gingivalis, which indicated that NOD1 played a non-negligible role in response to P. gingivalis-infection." (PMID 40016182, 2025). "To further investigate whether KLF5 is an effector of TNFRSF11a and whether KLF5 plays a role in TNF-α-induced CC cell functions, we overexpressed KLF5 in HeLa cells through infection with a specific adenovirus (Ad-KLF5)." (PMID 29146991, 2017). "Consistent with the immunohistochemistry results, infection with wild-type strain PMSS1 or the PMSS1 cagE− isogenic mutant induced similar increases in the percentage of KLF5+ cells and levels of KLF5 protein, confirming that induction of KLF5 occurs in a cagE-independent manner." (PMID 23372710, 2013). "Infection of these gRNA-expressing A549-AC lines with SARS-CoV-2 at various MOI conditions produced consistent phenotypes: (i) knocking out pro-viral ATP6V0D1 or DPAGT1 increased cell viability and (ii) knocking out anti-viral DAZAP2, VTA1, or KLF5 decreased cell viability." (PMID 38168026, 2024).
adenocarcinoma (5 papers, 2017 to 2025). A common cancer characterized by the presence of malignant glandular cells. "Collectively, our observations add to an increasing body of evidence that distinguishes basal identity from mesenchymal identity in adenocarcinoma biology, with the former retaining dependencies on epithelial oncoprotein TFs like KLF5 and ΔNp6356,69." (PMID 41241675, 2025).
kidney diseases (5 papers, 2021 to 2024). "A recent study has reported that KLF5 controls podocyte apoptosis, kidney cell proliferation, tubulointerstitial inflammation, and kidney fibrosis in renal diseases." (PMID 36358467, 2022). "Therefore, a systemic investigation of KLF5’s roles in these renal diseases and potential mechanisms underlying its actions is urgently needed and this may provide important novel targets for the prevention and treatment of some renal diseases." (PMID 33523554, 2021). "In this review, we have summarized the current evidence confirming an important role for KLF5 in various kidney diseases and we have discussed the possible mechanisms regulating KLF5 expression transcriptionally or translationally." (PMID 33523554, 2021). "KLF5 promotes inflammatory response in kidney disease by promoting activation of pro‐inflammatory M1‐type macrophages." (PMID 33523554, 2021). "Although, the role for KLF5 in mediating kidney disease is established, the studies involving KLF5 transcriptional, post‐transcriptional and post‐translational modifications in the kidney are limited." (PMID 33523554, 2021). "KLF5 contributes to the preservation of podocyte function and prevention of apoptosis through the regulation of crucial pathways, which are pivotal in the context of kidney diseases." (PMID 38892221, 2024). "KLF5 has been demonstrated to regulate tubulointerstitial inflammation in renal diseases." (PMID 38515158, 2024). "In summary, although the KLF5 pathogenic mechanisms of various renal diseases have not been well characterized, its involvements in several renal diseases have clearly emerged." (PMID 33523554, 2021). "The studies in the kidney, demonstrate that KLF5 modulates kidney diseases by regulating a variety of cellular responses including apoptotic cell death, inflammation, cell proliferation and fibrosis, making KLF5 a plausible therapeutic drug target to treat kidney diseases." (PMID 33523554, 2021). "KLF5 could also be regulated by many other activators and repressors which are related to kidney disease." (PMID 33523554, 2021). "Furthermore, we also have outlined the current and possible mechanisms of KLF5 activation in kidney diseases." (PMID 33523554, 2021). "Further studies in the kidney are needed to delineate the mechanisms by which KLF5 regulates inflammation in a variety of kidney diseases and identifying these precise mechanisms may lead to generation of therapies to control inflammation‐mediated kidney injury/disease." (PMID 33523554, 2021). "Furthermore, IL‐1β, HIF‐1α and C3a, known regulators of kidney disease, could induce KLF5 expression." (PMID 33523554, 2021). "The mechanistic studies that precisely define KLF5 regulation of kidney diseases are not completed known." (PMID 33523554, 2021). "Although oxidative stress promotes inflammation, apoptosis and fibrosis in kidney disease, no study to date has examined a direct link between oxidative stress and KLF5 expression in the kidneys." (PMID 33523554, 2021). "However, this study was performed with a cell culture model and so far, there are no studies performed in animal models of kidney disease that have explored the expression of KLF5 in podocytes." (PMID 33523554, 2021).
vasculopathy (5 papers, 2018 to 2021). "Taken together, PTMs regulate KLF5 function and transcriptional activity, and a better understanding of PTMs is particularly important for the study of vascular disorders and the development of therapeutic agents." (PMID 33493334, 2021). "We propose that with further studies, epigenetic changes of KLF5 expression can become biomarkers of vascular disorders, and targeted molecules (e.g. demethylating agents) will serve as therapeutic strategies." (PMID 33493334, 2021). "As a result, identification of KLF5 binding partners and gene targets and elucidation of KLF5 biological functions will better develop prevention and therapy of vascular disorders." (PMID 33493334, 2021). "Targeting the Klf5-eIF5a/Mfn1 regulatory pathway provides a potential therapeutic strategy for age-related vascular disorders." (PMID 32817651, 2020). "Considering its essential functions, KLF5 could be developed as a potent therapeutic target in vascular disorders." (PMID 33493334, 2021). "KLF5 plays a promising role in the treatment of vascular disorders." (PMID 33493334, 2021). "Additionally, importantly for SSc-related vasculopathy, KLF5 promotes angiogenesis through directly regulating VEGFA transcription." (PMID 31582779, 2019). "However, the mechanisms of KLF5 action in vascular remodeling are still far from clear, and most approaches targeting KLF5 (e.g. miRNAs, antibodies, and inhibitors) in vascular disorder treatment are based on cell or animal experiments, while their clinical safety and effect are still obscure." (PMID 33493334, 2021).
gastrointestinal tumors (4 papers, 2021 to 2025). "In liver sinusoidal endothelial cells, curcumol alleviates chronic liver injury via reducing the production of mitochondrial ROS and suppressing of KLF5-mediated liver angiogenesis." (PMID 38914581, 2024). "Through bioinformatics analysis, the functions and roles of KLF4 and KLF5 are further elucidated in gastrointestinal tumors." (PMID 34367275, 2021). "KLF4 and KLF5 are of great significance for developing gastrointestinal tumors and can be used as therapeutic targets." (PMID 34367275, 2021). "Bioinformatics was used for analysis to understand the function and roles of KLF4 and KLF5 in gastrointestinal tumors." (PMID 34367275, 2021). "KLF5 is highly expressed in gastrointestinal tumors, and the low expression in COAD, READ, and STAD was statistically significant (P < 0.05)." (PMID 34367275, 2021). "KLF4 and KLF5 are members of the KLF transcription factor family, which play an important role in many gastrointestinal tumors." (PMID 34367275, 2021). "KLF5, in contrast to KLF4, showed high expression in gastrointestinal tumors." (PMID 34367275, 2021).
inflammation (2 papers, 2013 to 2022). Aberrant reaction of the microcirculation characterized by movement of fluid and leukocytes from the blood into extravascular tissues. "We demonstrated that mice with intestinal epithelium–specific deletion of Krüppel-like factor 5 (Klf5) developed Th17-dependent colonic inflammation." (PMID 35393949, 2022). "Despite differences in levels of gastric inflammation in mice infected with PMSS1 versus the cagE− isogenic mutant, both strains induced significantly increased levels of KLF5 compared to uninfected controls." (PMID 23372710, 2013).
bacterial infection (1 paper, 2025). "Together, these data identify Klf5 as a direct and functional transcriptional regulator of Tgr5 and suggest that Tgr5 expression is dynamically regulated during bacterial infection and inflammation." (PMID 41377671, 2025).
respiratory diseases (1 paper, 2021). "Thus, as previously reported, KLF5 serves as an inducer of respiratory diseases." (PMID 34118928, 2021).